PRSS47P (serine protease 47, pseudogene)
Synonyms: PRSS47
Gene: Transcribed unprocessed pseudogene on chromosome 9 (92,177,235 to 92,189,635, reverse strand). Ensembl gene ENSG00000276717.
Subcellular location: Secreted